SULF2 (sulfatase 2)
Diseases named in the same sentence as SULF2 in open-access papers (continued):
Sharing a sentence is not in itself a finding about the gene and the disease.
pancreatic adenocarcinoma (3 papers, 2007 to 2016). "To rigorously test the involvement of the Sulfs in Wnt signaling and tumor growth, we used lentiviral shRNA systems to silence Sulf-2 expression in four pancreatic adenocarcinoma cell lines." (PMID 17460759, 2007). "To determine if Sulf proteins were expressed by pancreatic adenocarcinoma in surgical specimens, we stained sections from seven archived cases with Sulf-1 and Sulf-2 antibodies and an IgG control." (PMID 17460759, 2007). "Our evidence for the involvement of the Sulfs in the growth and tumorigenesis of pancreatic adenocarcinoma cells is most complete for Sulf-2." (PMID 17460759, 2007). "Exposure of these pancreatic adenocarcinoma cells to a catalytically inactive form of Sulf-2 or siRNA-mediated silencing of endogenous Sulf-2 inhibited both Wnt signaling and cell growth." (PMID 17460759, 2007).
prostate carcinoma (3 papers, 2015 to 2020). A carcinoma that arises from epithelial cells of the prostate gland. "SULF1 is present in prostatic stromal cells in the transition regions between cancer and stroma and SULF2 chromosome locus is associated to prostate cancer susceptibility regions." (PMID 25887999, 2015). "SULF2 overexpression in prostate cancer cell lines has also been shown to increase cell migration and the expression of markers of epithelial to mesenchymal transition, changes important for metastasis." (PMID 27223083, 2016). "After analyzing the effects of SULF2 forced expression on the structure of HS from prostate cancer cells, we studied the differences on cell viability and migration." (PMID 25887999, 2015). "Since we have observed an increase of these characteristics on prostate cancer cells with forced expression of SULF2, we decided to analyze some EMT markers in these cells." (PMID 25887999, 2015). "As expected, after 2 days of culture, PC3 and DU-145 prostate cancer cells overexpressing SULF2 had already connected to fibroblasts, whereas the control cells transfected with empty vectors remained distant from fibroblasts." (PMID 25887999, 2015). "Consistent with this, prostate cancer cells overexpressing SULF2 presented an increase of WNT 3A and β-catenin double-stained cells, in addition to a nuclear location of β-catenin." (PMID 25887999, 2015). "DU-145 and PC3 prostate cancer cells overexpressing SULF2 presented an increase of 3-fold on the size of the colonies formed, compared to cells transfected with empty vector." (PMID 25887999, 2015). "To further investigate SULF2 role in tumorigenesis, we overexpressed such gene in prostate cancer cell lines." (PMID 25887999, 2015). "In summary, SULF2 overexpression increases metastatic prostate cancer cells growth and migration, leading to an augmentation of tumor colony formation and invasiveness." (PMID 25887999, 2015). "Hence, our results indicate that prostate cancer cells overexpressing SULF2 become more undifferentiated, which is in agreement with the increased cell growth and migration presented by them." (PMID 25887999, 2015). "Indeed, PC3 and DU-145 prostate cancer cells overexpressing SULF2 exhibited increased levels of CD44, vimentin, and N-cadherin." (PMID 25887999, 2015). "Thus, this study aimed to analyze the effects of the overexpression of SULF2 in prostate cancer cell lines via analyzing their viability, proliferation, migration and colony formation capabilities." (PMID 25887999, 2015). "Our results demonstrated a possible pro-tumorigenic role of SULF2 in prostate cancer." (PMID 25887999, 2015). "In order to determine whether SULF2 increase was able to exacerbate the tumorigenic phenotype of prostate cancer cells in vitro, PC3 and DU-145 cells were submitted to colony formation and transmigration assays." (PMID 25887999, 2015). "Our result showed that SULF2 is similarly expressed in normal and prostate cancer cells." (PMID 25887999, 2015). "Therefore, SULF2 appears to act as a proto-oncogene in prostate cancer cells, increasing their ability to growth and migrate." (PMID 25887999, 2015). "Moreover, DU-145 and PC3 prostate cancer cells with forced expression of SULF2 presented an augmentation of invasiveness and tumor colony formation in vitro." (PMID 25887999, 2015). "However, due to the limitations of in vitro experiments, further in vivo studies are necessary to better understand the complex function of SULF2 in prostate cancer." (PMID 25887999, 2015). "Therefore, SULF2 may contribute to the metastatic process in prostate cancer." (PMID 25887999, 2015). "The normal prostate epithelial cell line RWPE-1 and the prostate cancer cells DU-145, and PC3 were transfected with SULF2-expressing plasmid pcDNA3.1/Myc-His(−)-Hsulf-2." (PMID 25887999, 2015). "SULF2 gene expression was analyzed in RWPE-1 normal prostate epithelial cells and in LNCap, PC3 and DU-145 prostate cancer cells." (PMID 25887999, 2015).
prostate carcinoma (continued). "Interestingly, the knockdown of SULF2 reduced the cell viability of RWPE-1 normal prostate cells, as well as reduced the cell viability of DU-145 and PC3 prostate cancer cells." (PMID 25887999, 2015). "In addition, forced expression of SULF2 resulted in an increment of EMT markers and in a stronger contact between prostate cancer cells and stromal cells." (PMID 25887999, 2015). "Transfection of DU-145 and PC3 prostate cancer cells with SULF2 resulted in increased viability, which did not occur with normal prostate cells." (PMID 25887999, 2015).
rheumatoid arthritis (3 papers, 2024). A chronic, systemic autoimmune disorder characterized by inflammation in the synovial membranes and articular surfaces. "We then generated Sulf2+/− bone marrow chimeric mice and examined inflammatory responses in antigen-induced arthritis, as a model of rheumatoid arthritis." (PMID 39141086, 2024). "Given that rheumatoid arthritis is an autoimmune and inflammatory disease, it is possible that there is a link between SULF2 and immune-related cells like eosinophils." (PMID 38601075, 2024).
Arthritis (2 papers, 2024). Inflammation of a joint. "Using a bone marrow transplantation strategy, we generated chimeric mice with myeloid Sulf2-deficiency and examined inflammatory responses in vivo in an antigen-induced arthritis model." (PMID 39141086, 2024). "The effect of Sulf2-deficiency on myeloid function was then assessed using the antigen-induced arthritis (AIA) model, in which immunisation and boosting of mice with mBSA leads to myeloid and lymphoid cell-dependent joint inflammation and damage in mice." (PMID 39141086, 2024). "This was accompanied by an increased abundance of Th17 cells in joints of Sulf2+/− chimeras, consistent with the known ability of this subset to exacerbate inflammation in this and other models of arthritis." (PMID 39141086, 2024). "The in-silico drug design analysis was performed on biometabolites detected through GC–MS that might be a potential target for sulfatase-2 to treat ruminated arthritis." (PMID 38459108, 2024). "To understand how Sulf2-deficiency in macrophages could promote Th17 differentiation, we conducted bulk RNA sequencing of cells isolated from AIA joints during the resolution phase of joint inflammation." (PMID 39141086, 2024). "Sulf2+/− bone marrow chimeric mice showed significantly increased joint swelling and histological damage in the resolution phase of the macrophage- - and CD4+ T cell-dependent antigen-induced arthritis model." (PMID 39141086, 2024).
asthma (2 papers, 2015 to 2025). "scTWAS also uniquely identified SULF2 as significantly associated with asthma in plasma cells." (PMID 41256005, 2025). "Our findings provide evidence linking SULF2 to asthma pathogenesis, specifically through its potential role in plasma cells, and highlight it as a candidate for future functional studies and therapeutic exploration." (PMID 41256005, 2025). "Notably, while genetic variants in SULF2 gene have been associated with several diseases, there is currently no reported association with asthma or other lung diseases." (PMID 41256005, 2025).
Cirrhosis (2 papers, 2021 to 2023). A chronic disorder of the liver in which liver tissue becomes scarred and is partially replaced by regenerative nodules and fibrotic tissue resulting in loss of liver function. "The expression of SULF2 has also been reported in the plasma and serum of healthy individuals from peripheral blood mononuclear cells, and the overall plasma levels have been shown to be increased in cirrhosis." (PMID 33540508, 2021).
colon carcinoma (2 papers, 2006 to 2016). "SULF2 transcripts are upregulated in breast, central nervous system and colon carcinomas." (PMID 16417632, 2006).
gastric tumor (2 papers, 2013). "Based on previous studies,to analyze the methylation status of the promoter-associated CpG island of both WRN and SULF2, we collected 102 samples of primary gastric tumors." (PMID 24359226, 2013). "Our experiment demonstrated that SULF2 CpG island methylation renders gastric tumors sensitive to irinotecan." (PMID 24359226, 2013). "To this end, we performed a series of in vitro sensitivity tests on freshly-removed gastric tumor tissues and evaluated the possible use of SULF2 methylation status for predicting the chemotherapeutic efficacy of there agents." (PMID 24124496, 2013).
invasive ductal carcinoma (2 papers, 2014 to 2023). "HSULF-2 is a heparan sulfatase-2 protein that exhibits 6-O-endo-sulfatase activity and that is differentially overexpressed on the surface of most cancer cell lines and is also found to be upregulated at the transcriptional level in ductal carcinoma in situ and invasive ductal carcinoma." (PMID 36644581, 2023).
liver disease (2 papers, 2021 to 2024). "We therefore aimed to elucidate the mechanistic role of SULF2 in fibrotic liver disease by examining its relationship with TGF-β." (PMID 34771445, 2021). "Furthermore, SULF2 is significantly elevated in the serum of individuals with cirrhotic liver disease." (PMID 34771445, 2021). "We demonstrate here that SULF2 exerts its effect on fibrotic liver disease via its interplay with the TGF-β1/Smad pathway and that the TGFBR3 likely plays an important role in the SULF2 mediated activation of the TGF-β1 signaling pathway." (PMID 34771445, 2021). "SULF2 influences fibrotic liver disease by interacting with the TGF-β1/Smad pathway, and it appears that Transforming Growth Factor Beta Receptor 3 (TGFBR3) plays a significant role in mediating the activation of the TGF-β1 signaling pathway by SULF2." (PMID 38540990, 2024).
lymph node metastasis (2 papers, 2013 to 2017). "Advanced pT stages, lymph node metastasis, high grade present high SULF2 expression in UBUC significantly." (PMID 28525382, 2017). "Renal pelvis location, single site tumor, advanced pT stages, lymph node metastasis, high grade, vascular invasion, higher mitotic rate present high SULF2 expression in UTUC significantly." (PMID 28525382, 2017).
multiple sclerosis (2 papers, 2021 to 2024). A progressive autoimmune disorder affecting the central nervous system resulting in demyelination. "We found that Sulf2 was increased in demyelinating lesions in multiple sclerosis and was actively secreted by human OPCs." (PMID 33772011, 2021).
neuroblastoma (2 papers, 2016 to 2022). Neuroblastoma (NB) is the most common solid, extracranial childhood tumor. "SULF1 expression in fibroblast cells is distinctly higher compared with all the cancer cell lines but SULF2 expression is the highest in cell lines from neuroblastoma, HNSC, and other cancers." (PMID 36428645, 2022). "Suppression of SULF-2 using small interference RNA (siRNA) decreased cell proliferation in MYCN-amplified neuroblastoma cells, indicating that SULF-2 is a potential drug target." (PMID 26771642, 2016). "The protein sulfatase 2 (SULF-2) is overexpressed in MYCN-amplified neuroblastoma cells but expressed at a much lower level in MYCN-unamplified cells." (PMID 26771642, 2016). "A SULF-2 small molecule inhibitor, OKN-007, has been developed, but has yet to be examined in neuroblastoma." (PMID 26771642, 2016).
oral cavity tumors (2 papers, 2020 to 2024). "SULF2 mRNA has highest expression in oral cavity tumors which is significantly higher than the expression in the larynx (p = 0.006) and in the oropharynx (p < 0.001)." (PMID 33585200, 2020). "HNSCC cell lines SCC35 and CAL33 (human squamous cell carcinoma cell lines derived from hypopharynx and oral cavity tumors, respectively) conditioned media was used as the starting material for immuno-affinity purification (IP) of the Sulf-2 protein in complex with its interacting partners." (PMID 38825040, 2024).
ovarian carcinoma (2 papers, 2010 to 2022). A malignant neoplasm originating from the surface ovarian epithelium. "An overlapping set of seven genes (ABCB1, APC, BRCA1, CDH1, DNAJC15, HIC1 and SULF2) displayed the same methylation changes in the examined set of ovarian carcinoma cell lines." (PMID 20544021, 2010). "In case of the ovarian carcinoma cell lines OVCAR-5, OVCAR-4 and NCI/ADR-RES, the methylation status of CGIs associated with the genes ABCB1, BRCA1, CDH1, DNAJC15, and SULF2 was connected to the expression of the genes." (PMID 20544021, 2010). "In contrast, ovarian cancer patients with high RNA levels of SERPINE1, SULF2, FOXL2, and CARD16 live longer in comparison with ovarian cancer patients with lower levels of these RNA transcripts." (PMID 35008958, 2022).
psoriasis (2 papers, 2019 to 2024). An autoimmune condition characterized by red, well-delineated plaques with silvery scales that are usually on the extensor surfaces and scalp. "We observed the upregulation of CMKLR-1, COL8A-1, NETO-2, NRK, SYTL-2, and SULF-2 in dermal mesenchymal stem cells derived from patients with psoriasis at both mRNA and protein level, however, a significant downregulation of SFRP-2 between two groups." (PMID 30760317, 2019). "Our findings suggest it is worth investigating whether Sulf2 could also be protective in other autoimmune conditions where IFNβ signaling promotes Th17-driven inflammation e.g. psoriasis, systemic lupus erythematosus, Sjögren’s syndrome, and neuromyelitis optica." (PMID 39141086, 2024).
skin cancer (2 papers, 2011 to 2023). "When researching the effects of sulforaphane in mice models of skin cancer, Alyoussef and Taha found that sulforaphane blocked sulfatase-2 activity which, when activated, significantly elevated heparan sulfate proteoglycan concentration in plasma." (PMID 37299535, 2023).
squamous cell carcinoma (2 papers, 2016 to 2024). A carcinoma arising from squamous epithelial cells. "In contrast, there was a significant decrease in the risk of death (89%; p = 0.02) for patients with squamous cell carcinoma with SULF2 staining in tumor cells." (PMID 26882224, 2016). "Surprisingly, SULF2 staining of tumor cells in patients with squamous cell carcinoma was associated with a better survival rate." (PMID 26882224, 2016).
type 2 diabetes (2 papers, 2013 to 2022). "So far, data on the role of SULF2 variants in humans is limited to an abstract report of subjects with type 2 diabetes, in whom SULF2 rs2281279 was associated with the levels of both fasting and postprandial TRLs." (PMID 24278138, 2013). "Furthermore, in mice with type 2 diabetes, uptake of remnant lipoproteins is suppressed by accelerated degradation of HSPG owing to the hepatic induction of a heparan sulfate 6-O-endosulfatase (SULF2)." (PMID 24278138, 2013).
actinic keratosis (1 paper, 2023). A precancerous lesion of the skin composed of atypical keratinocytes. "Five new genes, HEPHL1, FBN2, SULF1, SULF2, and TCN1, were recently discovered in cSCC, which were significantly upregulated compared to normal skin (p < 0.001) and actinic keratosis (AK) (p < 0.01)." (PMID 36980718, 2023).
Alzheimer disease (1 paper, 2021). A progressive, neurodegenerative disease characterized by loss of function and death of nerve cells in several areas of the brain leading to loss of cognitive function such as memory and language. "Decreased expression of SULF2 was found in Alzheimer's disease patients indicating its implication in regulating neuronal signaling." (PMID 34427971, 2021).
atherosclerosis (1 paper, 2022). A disease characterized by the build-up of fatty material and calcium deposition in the arterial wall resulting in partial or complete occlusion of the arterial lumen. "Characterisation of Sulf1/Sulf2 functional heterogeneity has clinical implications not only in angiogenic cell signalling but also in the prevention or reduction of thrombosis and atherosclerosis, which requires further studies." (PMID 35409127, 2022).
bladder (1 paper, 2022). "We constructed a SULF2 knockdown stable transgenic cell line of MB49 mouse cells and constructed a bladder orthotopic cancer model in C57 mice." (PMID 36612128, 2022).
brain tumors (1 paper, 2015). "SULF2, a heparan sulfate endosulfatase, has been associated to different types of cancers including lung, breast, liver, gastric, and brain tumors." (PMID 26248280, 2015).
cholangiocarcinoma (1 paper, 2022). A carcinoma that arises from the intrahepatic biliary tree (intrahepatic cholangiocarcinoma) or from the junction, or adjacent to the junction, of the right and left hepatic ducts (hilar cholangiocarcinoma). "SULF2 is upregulated and oncogenic in various cancers and a recent study documented that anti-SULF2 antibodies prevent tumor growth in a mouse model of cholangiocarcinoma." (PMID 36428645, 2022).
chronic asthma (1 paper, 2025). An asthma that is characterized by the development of persistent airway inflammation and recurrent attacks of breathlessness and wheezing, which vary in severity and frequency. "Known for its role in modifying heparan sulfate proteoglycans, SULF2 can impact key biological processes such as cell signaling, inflammation, and tissue remodeling, including airway remodeling, a hallmark of chronic asthma." (PMID 41256005, 2025).
depression (1 paper, 2022). "Sulfatase 2 is crucial for brain development, contributing to processes such as neurite outgrowth and responsiveness to growth factors, and there is an association between SULF2 variants and HSV-1 and depression risk, and also with malaise and fatigue in UK Biobank studies." (PMID 36517845, 2022).
diabetic nephropathy (1 paper, 2021). "In addition, a recent study reported critical roles for SULF1 and SULF2 in the maintenance of glomerular integrity and their protective roles in diabetic nephropathy." (PMID 33540508, 2021).
fibrosis (1 paper, 2021). the formation of excess fibrous connective tissue in an organ or tissue in a reparative or reactive process. "Together, these data suggest that SULF2 regulates liver fibrosis via the TGF-β signaling pathway." (PMID 34771445, 2021).
high blood pressure (1 paper, 2013). "SULF1 and SULF2 (another protein in this family) double knockout mice show impairment in skeletal development, but whether they display high blood pressure has never been explored." (PMID 23325143, 2013).
Insulin resistance (1 paper, 2016). Increased resistance towards insulin, that is, diminished effectiveness of insulin in reducing blood glucose levels. "Insulin resistance has been reported to associate with diminished remnant clearance by impairing the HSPG structure via modulation of hepatic SULF2 expression and by altering LDL receptor via PCSK9." (PMID 27686975, 2016).
ischemia (1 paper, 2021). A hypoperfusion of the BLOOD through an organ or tissue caused by a PATHOLOGIC CONSTRICTION or obstruction of its BLOOD VESSELS, or an absence of BLOOD CIRCULATION. "To examine if some changes in cell signalling or Sulf1/Sulf2 levels during in vivo ischemia were also apparent during in vitro hypoxia, we exposed HMec1 human endothelial cells to 100 μM and 300 μM CoCl2 chemical hypoxia for different lengths of time to examine changes in VEGF levels." (PMID 34789772, 2021).